IGFBP6 (insulin like growth factor binding protein 6)
Diseases named in the same sentence as IGFBP6 in open-access papers (continued):
Sharing a sentence is not in itself a finding about the gene and the disease.
skin cancer (1 paper, 2022). "Notably, IGFBP6 expression was significantly correlated with the prognosis of seven types of cancer, including blood, breast, brain, colorectal, ovarian, lung, and skin cancer." (PMID 35832140, 2022).
tendinopathy (1 paper, 2022). "Previously, there have been a few reports of differential promoter methylation of Mmp25, Foxf1, Leprel2, Igfbp6 and Peg12 in tendinopathy through genome-wide analysis." (PMID 35860629, 2022).
viral hepatitis (1 paper, 2026). An acute or chronic inflammation of the liver parenchyma caused by viruses. "Viral hepatitis provides a clear example of post-translational control: O-β-GlcNAc modification of IGFBP-6 at Ser204 reduces IGF-II binding, implying that inflammatory and metabolic fluxes through the hexosamine pathway can shift IGFBP-6’s capacity to sequester IGF-II in infected livers." (PMID 41511360, 2026). "Mechanistically, IGFBP-6 can be O-β-GlcNAc-modified at Ser204 during HBV/HCV infection, diminishing IGF-II binding and potentially increasing free IGF-II, which contextualizes how inflammatory/metabolic fluxes may tune IGFBP-6 function in chronic viral hepatitis." (PMID 41511360, 2026).
tumor (60 papers, 2008 to 2026). "IGFBP-6 has also been implicated in a wide variety of fibrotic diseases of the skin, heart, lung, kidney, and liver, and contributes to cancer stroma in the tumor microenvironment which is mediated at least partially by interactions with TGF- β." (PMID 41226289, 2025). "This identified multiple genes downregulated in tumour-associated adventitial fibroblasts compared to control counterparts, including IGFBP6, FABP4 and DCN." (PMID 36720863, 2023). "Searching on miR-222 using miRConnect 2, identifies among other mechanistically associated genes TIMPs and Insulin-like growth factor binding protein 6 (IGFBP6) with known functional roles in tumor cell migration and invasion." (PMID 28091986, 2017). "Furthermore, IGFBP6 has been associated with GBM tumor cell chemoresistance, tumor-supportive TAM polarization and immune escape." (PMID 37314567, 2023). "But as a tumor suppressor gene, IGFBP6 was associated with activation of MAPK signaling pathway." (PMID 37950222, 2023). "Therefore, in the next paragraph, we will discuss IGFBP-6 signaling in the tumor microenvironment (TME), which harbors cancer-associated fibroblasts, leading to angiogenesis, fibrosis, and immune evasion." (PMID 35457175, 2022). "Nonsense mutations are often not directly associated with RNA decay, however RNA-seq analysis showed significant upregulation of downstream transcripts in the SMO-SUFU-GLI pathway, including those encoding MDM2 and IGFBP6, which are associated with tumor proliferation." (PMID 31023376, 2019). "This post-translational change dovetails with experimental evidence that IGF signaling fosters stem-like phenotypes and self-renewal in HCC models, indicating a plausible route by which infection-linked glycosylation of IGFBP-6 could feed forward into tumor aggressiveness." (PMID 41511360, 2026). "A deeper analysis revealed upregulation of genes involved in tumor suppression (Clca2, Spink5, Igfbp6, Nptx1, Bex4, Gadd45g, Yipf5), immune regulation (IL6ra, Ccl6, Cd81, Cd244a, Cd151, and Gata4), apoptosis, and pyroptosis (Ddit3, Rgs6, and Gsdmsc2/3/4)." (PMID 39946195, 2025). "In our bioinformatics analysis, we observed that OSMR and FMOD were mainly distributed in astrocytes in GBM tumor tissue, while IGFBP6 was predominantly found in NPC cells, all of which are crucial factors in GBM pathogenesis." (PMID 39815665, 2025). "This review highlights emerging evidence that IGFBP-6 functions as a redox-sensitive modulator of immune activation, fibrosis, and tumor biology, acting through both IGF-dependent and IGF-independent mechanisms." (PMID 40723309, 2025). "Insulin-like growth factor IGF1 and insulin-like growth factor binding protein IGFBP6 exert contrasting effects on tumor cells, with pro-tumor and anti-tumor effects, respectively." (PMID 38818409, 2024). "The results presented demonstrate that IGFBP-6 is a tumor suppressor gene in hormone receptor positive breast cancers." (PMID 39698031, 2024). "Meanwhile, BC with low IGFBP6 expression had a high probability of metastasis due to a more efficient invasion of tumor cells." (PMID 37950222, 2023). "Insulin-like Growth Factor Binding Protein-6 (IGFBP-6) is expressed during tumor development, and is involved in immune-escape and inflammation as well, providing a potential additional target for CML therapy." (PMID 36836615, 2023). "It is generally accepted that IGFBP1, IGFBP4, and IGFBP6 inhibit tumor development and progression, and their antitumor activity is mainly ascribable to IGF sequestering." (PMID 37686233, 2023). "As the figure shown, P300 was positively related to NDUFAF6 and OVOL1, and negatively related to tumor suppress gene IGFBP6." (PMID 37950222, 2023). "In our study, we identified IGFBP6 as a tumor suppressor gene, which played a positive role in BC drug therapy and immunotherapy." (PMID 37950222, 2023).
tumor (continued). "The recombinant protein of insulin-like growth factor binding protein 6 (IGFBP6), regulated by lactate levels in tumors, regulates microglia polarization toward the M2 phenotype, in addition to enhancing the capability of tumor cells to migrate and aggregate." (PMID 37700840, 2023). "Among the known IGFBPs, IGFBP-6 shows an emerging role as a mediator of airway inflammation and tumor-suppressing activity in different lung tumors." (PMID 36902237, 2023). "Insulin-like Growth Factor Binding Protein 6 (IGFBP6) is expressed during tumor development, and it is involved in migration, immune-escape and inflammation, thus providing an attractive target for GBM therapy." (PMID 35654889, 2023). "The insulin-like growth factor binding protein 6 (IGFBP6) gene plays an important role in the pathogenesis of many malignancies, and is actively involved in proliferation, wound healing and the survival of tumor cells." (PMID 35204157, 2022). "IGFBP-6 is supposed to act as tumor suppressor and its concentration is lower in metastatic compared to non-metastatic CRC cells." (PMID 36013453, 2022). "Conversely, other studies have shown that the level of IGFBP6 is lower in tumor tissues than in normal cells, implying an antitumor effect of IGFBP6." (PMID 35204157, 2022). "IGF-independent actions of IGFBP-6 are mainly tumor protective and are considered as possible paths for cancer therapy." (PMID 36013453, 2022). "In this work, to study the changes in model tumor cells associated with the changes in the expression of the ELOVL5 and IGFBP6 genes, we decided to knock down the genes under consideration using RNA interference." (PMID 34149804, 2021). "To further characterize HS5 cells phenotype upon IGFBP-6 stimulation and the potential microenvironmental conditioning mediated by CAFs differentiation, we analyzed the expression levels of several tumor invasiveness and progression mediators." (PMID 34905501, 2021). "The increased expression of IGFPB6 inhibited the proliferation, invasion, and metastatic activity of the NPC cells, suggesting that IGFBP6 acts as a tumor suppressor." (PMID 34149804, 2021). "Overall, these results indicate that IGFBP‐6 effects on migration of tumour cells are based strongly on the tumorigenesis stage, although this should be corroborated by in vivo evaluation of tumour behaviour." (PMID 30117676, 2018). "Our results suggest that chemosensitive tumor cells are a source of IGFBP6, and secretion of this protein serves to inhibit GBM progression." (PMID 30231881, 2018). "On the basis of our findings, we propose that GBM tumor growth is characterized by a structured population with less aggressive clones (TMZ-sensitive-IGFBP6+-IFG-1R−) that block the expansion of more aggressive cells (TMZ-resistant-IGF2+IGF-1R+)." (PMID 30231881, 2018). "Using gain-of-function and loss-of-function strategies, we dissected the molecular mechanism responsible for IGF-binding protein 6 (IGFBP6) tumor suppressor functions both in in vitro and in vivo." (PMID 30231881, 2018). "On the basis of this observation, we tried to analyze a possible role of IGFBP6 in a chronic inflammatory disorder such as RA, where pannus development and cartilage and bone damage at the joint level recall tumor development and invasion." (PMID 28572803, 2017). "We injected CNE2 cells transfected with either ctrl-shRNA or IGFBP6-shRNA into the left ventricles of severe combined immunodeficiency (SCID) mice to assess tumor cell metastasis." (PMID 27623076, 2016). "We knocked down endogenous IGFBP6 in CNE2 cells to assess tumor cell growth, invasion and metastasis in vitro and in vivo." (PMID 27623076, 2016). "Mice injected with IGFBP6-shRNA-transfected cells had higher metastasis rates, and tumor cells metastasized to multiple distant organs, such as liver, lung, bone, kidney and intestine." (PMID 27623076, 2016).
tumor (continued). "In vivo experiments using the RMS cell line RH30 have shown that IGFBP-6 overexpression resulted in a marked delay in tumor growth in nude mice." (PMID 21437217, 2011). "In addition to functional crosstalk, there is primary evidence that canonical Wnt/β-catenin signaling can directly regulate IGFBP-6 transcription in fibroblast-like tumor settings." (PMID 41511360, 2026). "IGFBP-6 enhances oxidative burst in neutrophils, contributes to fibroblast senescence and activation under oxidative stress, and reprograms mitochondrial metabolism and antioxidant responses in tumor cells." (PMID 40723309, 2025). "In addition, IGFBP-6 also induces metastasis and acts as a homing signal for circulating tumor cells." (PMID 41375025, 2025). "IGFBP6 has been reported to act as both a tumor suppressor and a promoter of several cancers, but its role in PTC is unknown." (PMID 40430098, 2025). "Mechanistically, IGFBP-6 has been shown to influence mitochondrial metabolism in tumor cells." (PMID 40723309, 2025). "explored the interaction between lactate and Lnsulin-like Growth Factor-binding Protein 6 (IGFBP6) in GBM cells, revealing that lactate can regulate IGFBP6 expression, further modulating microglial polarization and contributing to tumor development and therapeutic resistance." (PMID 39877360, 2024). "Similarly, the analyses of IGFB6 mRNA expression in normal ovary and EOC samples showed a sharp IGFBP6 reduction in tumor samples, especially metastatic lesions." (PMID 38658801, 2024). "Among various growth factors, IGFBP6 was reported to play an important role in survival and migration of tumor cells, but its effects on tumor and immune system interaction are still poorly understood and the relationships between IGFBP6 and cancer prognosis remain contradictory in many studies." (PMID 35654889, 2023). "Among the most interesting biological processes reshaping cell metabolism, those that recap developmental processes, such as the one involving IGFBP6, hold great potential to understand tumor-related biological processes such as cell proliferation, migration, senescence and changes in metabolism." (PMID 35654889, 2023). "Particular attention was paid to the study of the role of IGFBP6 in tumor metastasis." (PMID 36714261, 2023). "Moreover, by analyzing the distinct expression patterns and prognostic values of IGFBP family members in patients with NSCLC with bioinformatics tools, IGFBP-6 was downregulated in tumor samples as a result." (PMID 36902237, 2023). "In addition, we uncovered that the expression of MYBPH and IGFBP6 expression was appreciably connected to tumor prognosis." (PMID 36193073, 2022). "Some studies have indicated that IGFBP-6 could inhibit tumor angiogenesis in multiple systems through the IGF-2-independent pathway." (PMID 36193073, 2022). "Among the most interesting biological processes reshaping cell metabolism, those that recap developmental processes through IGFBP6 involvement hold great potential to understand tumor-related biological processes, such as cell proliferation, wound healing, senescence, and changes in metabolism." (PMID 35204157, 2022). "Respectively, depending on particular cell type, effects of IGFBP6 may be classified as that of a tumor suppressor, or a facilitator of the metastatic spread." (PMID 31781574, 2019). "When UTMZ cells were injected into the flank of nude mice, the mean tumor weight was significantly lower (0.18 ± 0.09 g vs 0.92 ± 0.1 g) in the group that received IGFBP6-transfected UTMZ cells than in the control group that received empty vector-transfected UTMZ cells." (PMID 30231881, 2018). "Considering the IGFBP6 ability to promote tumor cell migration, the overexpression of IGFBP6 in ST may suggest its relevance for immune cell migration into inflammatory environment." (PMID 28572803, 2017). "IGFBP6 was downregulated in HF offspring, and it acts as a tumor suppressor." (PMID 28673325, 2017).
tumor (continued). "In recent years, the protein IGFBP6 has been extensively investigated in tumor biology." (PMID 28572803, 2017). "IGFBP6 knockdown in CNE2 cells promoted tumor cell metastasis in vivo." (PMID 27623076, 2016). "Only one in vitro study proposed that IGFBP6 is a tumor suppressor in NPC." (PMID 27623076, 2016). "Furthermore, the overexpression of IGFBP-6 resulted in a 74–88% reduction in Rh-30 tumor size in vivo after 18 days, showing that IGFBP-6 can be a potent antitumor agent." (PMID 21197468, 2011). "Thus, the increase in MMP1 and MMP3 expression observed after the knockdown of the ELOVL5 and IGFBP6 genes is consistent with the hypothesis that ELOVL5 and IGFBP6 are associated with tumor metastatic potential." (PMID 34149804, 2021). "We investigated whether IGFBP6 influenced tumor cell proliferation and invasion in vitro." (PMID 27623076, 2016). "This suggests that the protein expression of OSMR, IGFBP6, and IGHG2 was significantly elevated in the tumor tissue of GBM patients compared to normal control tissue." (PMID 39815665, 2025). "The results indicated that in GBM tumor tissue, OSMR and FMOD were primarily distributed in astrocytes, IGFBP6 in NPC, G0S2 in macrophages, and IGHG2 in T cells." (PMID 39815665, 2025). "To investigate the role of the five genes (OSMR, G0S2, IGFBP6, IGHG2, and FMOD) in specific cells within the tumor tissue of GBM patients, we illustrated the distribution of these genes across different cell types." (PMID 39815665, 2025). "In the HPA database, only OSMR, IGFBP6, and IGHG2 were found, showing high levels of protein expression in tumor tissue of GBM patients for all three." (PMID 39815665, 2025). "Since lactate promotes tumor proliferation and migration in GBM cells, we evaluated the effect of lactate on IGFBP6 expression and the effect of IGFBP6 exposure in three human GBM lines (i.e. U-87 MG, A-172 and U-251 MG)." (PMID 35654889, 2023). "In particular, we assessed the relationship between the immunohistochemical expression of IGFBP6 and MIB-1, a widely used marker of the tumor proliferative activity, and found a positive correlation between these two markers." (PMID 35654889, 2023). "Further research will help shed light on the detailed molecular mechanisms responsible for the observed changes in tumor cell properties resulting from a decreased expression of the ELOVL5 and IGFBP6 genes." (PMID 34149804, 2021). "Moreover, inhibitor of growth, i.e. Tgfb1, Gadd45b, Igfbp6, A-kinase-anchoring protein (Akap12) and protein tyrosine phosphatase, non-receptor type substrate 1 were highly significantly repressed, from which their important role in tumor progression can be inferred." (PMID 29254206, 2017). "The insulin-like growth factor binding protein 6 (IGFBP6), a direct inhibitor of insulin-like growth factor (IGF)-II, also exerts IGF-independent effects including tumor cell migration in vitro." (PMID 28572803, 2017). "IGFBP6 knockdown activated the GSK3β/β-catenin/cyclin D1 pathway and enhanced CNE2 tumor cell growth and metastasis in a mouse model." (PMID 27623076, 2016). "IGFBP3 and IGFBP6 are IGF-binding proteins that inhibit IGFs, therefore functioning as tumor suppressors." (PMID 24920244, 2014). "Notably, in fibroblast-derived desmoid tumor cells, stabilized β-catenin/TCF represses IGFBP-6 via TCF-responsive promoter elements." (PMID 41511360, 2026). "Broader tumor-stromal studies show that CAFs secrete IGF/IGFBP ligands that rewire signaling and drug response in adjacent cancer cells, supporting a mechanistic niche for stromal IGFBP-6 in liver tumor microenvironments." (PMID 41511360, 2026). "Based on these findings, it can be hypothesized that IGFBP6 may be used in the future as easily detectable prognostic marker of GBM, predictor of increased tumor aggressiveness." (PMID 35654889, 2023). "The results indicated that the protein expression of IGFBP6 and IGFBP7 could be detectable in all 20 types of tumor tissues." (PMID 37088808, 2023).